BRAF (B-Raf proto-oncogene, serine/threonine kinase)
Diseases named in the same sentence as BRAF in open-access papers (continued):
Sharing a sentence is not in itself a finding about the gene and the disease.
melanoma (continued). "Although these approvals certainly represent significant therapeutic options for patients with metastatic melanoma, there are fewer treatment options for patients with non-BRAF mutant melanomas." (PMID 25915038, 2015). "We find that inhibition of BRaf in melanoma cell lines leads to compensatory signaling via ErbB family members, which are RTKs." (PMID 26405815, 2015). "On the horizon are various new products for advanced melanoma, including the PD-1 blockade treatments nivolumab and pembrolizumab, and BRAF/MEK combination therapies." (PMID 26700304, 2015). "In the preceding analysis, DNMT3A also exhibited significantly elevated expression levels in the A375 melanoma cells after being induced with the BRAF inhibitor." (PMID 25890285, 2015). "Inhibition of PI3K alone with ZSTK474 or PI3K and mTOR with BEZ235 was effective at inhibiting cell proliferation and AKT signaling in all BRAF-mutant melanoma cell lines." (PMID 26137449, 2015). "To date, several mechanisms of resistance to targeted therapies (mostly, BRAF-mutant inhibitors) have been reported in melanoma." (PMID 26322273, 2015). "Mutations in BRAF (at position V600) and NRAS (G12/13, Q61) are responsible for 50 and 20% of melanomas, respectively." (PMID 26424083, 2015). "The BRAF (V600E)-MITF-PGC1-alpha axis promotes the biogenesis of mitochondria and causes BRAF-mutant melanoma cells to become addicted to mitochondrial metabolism." (PMID 26445347, 2015). "Overall these data show that RHOB depletion triggers caspase-dependent apoptosis of BRAF-mutant melanoma cells exposed to MAPK inhibitors." (PMID 26098773, 2015). "On the basis of the METRIC study, treatment with trametinib is associated with longer PFS when compared with chemotherapy (dacarbazine or paclitaxel) in patients with BRAF V600 E/K mutant melanoma." (PMID 26171394, 2015). "Induction of ROS has indeed been proposed as an effective way of killing melanoma cells, especially of those that are resistant to BRAF inhibitors like vemurafenib." (PMID 26029997, 2015). "This is exemplified by the differential activation of EGFR-driven feedback control in BRAF-mutant colorectal cancer and melanomas in response to BRAF inhibition." (PMID 25885672, 2015). "Despite these remarkable results, response to BRAF inhibitors is transient for most patients with advanced melanoma." (PMID 25886620, 2015). "As such, the simultaneous inhibition of both BRAF and EZH2 should be considered in treatment of melanoma patients that harbor these mutations." (PMID 25671303, 2015). "Treatment with nanomolar levels of mTOR inhibitor, however, rendered these cells as sensitive to MEK inhibition as melanoma with mutant BRAF." (PMID 25955301, 2015). "For 420 melanoma samples tested, the cobas method versus HBM showed a high concordance (93.3%; kappa = 0.86) in BRAF V600 genotyping with similar mutation rates (34.0% versus 35.7%, respectively)." (PMID 25789737, 2015). "The major pathways in melanoma signaling mediated through BRAF, WNT/β-catenin and Akt-NF-κB converging in MITF-M, the master regulator of melanomagenesis, were inhibited by DW-F5, leading to complete abolition of MITF-M." (PMID 26061820, 2015). "For patients with melanoma, the concept of potential synergy with BRAF-targeted therapy and immunotherapy is being empirically investigated in clinical trials; however, much remains to be learned." (PMID 25895031, 2015). "Circulating mutant NRAS presumably originates from a subset of the melanoma burden, and this is supported by the fact that NRAS mutant ctDNA was consistently lower than the BRAF mutated ctDNA." (PMID 26524482, 2015). "Based on our findings, we suggest combining vemurafenib with complex I inhibitors in BRAF mutant melanoma in order to diminish the ability of cancer cells to adapt to either agent." (PMID 26500770, 2015).
melanoma (continued). "Treatment of melanoma cells with increasing concentrations of vemurafenib resulted in a dose-dependent inhibition of proliferation of the BRAF V600E mutant melanoma cell lines 518A2 and M14." (PMID 25997619, 2015). "This case describes an unique hyperacute onset of tumour progression correlating with an acute deterioration of neurological symptoms in a patient suffering from miliary brain metastasis from BRAF positive malignant melanoma." (PMID 26187589, 2015). "Melanoma cell lines expressing either mutated RAS or mutant BRAF were equally sensitive to GSK3 inhibition, as were cell lines resistant to the BRAF inhibitor Vemurafenib." (PMID 25915038, 2015). "In resistant melanoma cell lines, vemurafenib (BRAF inhibitor) or selumetinib (MEK inhibitor) either fail to suppress P-ERK or resistance emerges through the activity of mammalian target of rapamycin (mTOR), despite P-ERK suppression and BIM induction." (PMID 26639561, 2015). "Gab2 amplification is associated with melanoma arising from sun-protected sites and often occurs independently from oncogenic NRAS or BRAF mutations or amplifications of the KIT gene." (PMID 26095858, 2015). "One of the latest successful drugs for the treatment of advanced melanoma is the BRAF inhibitor vemurafenib (also known as PLX4032) that showed an increase in overall survival and an extension of progression-free survival." (PMID 25997619, 2015). "Gene mutation status of BRAF, PIK3CA, PTEN, and hTERT and protein expression of PTEN and pAKT in the melanoma cell line panel." (PMID 26137449, 2015). "Recent studies have demonstrated BRAF to be important for tumor growth and maintenance in melanoma models, whereas BRAF seems to possess relatively low oncogenic activity as compared to RAS and PI3K." (PMID 25784655, 2015). "We have been the first to show that activation of the ErbB3/AKT axis in melanoma can be inhibited by co-treatment with anti-ErbB3 mAbs and that these antibodies synergize with BRAF and MEK inhibitors in short term in vitro clonogenic assays." (PMID 26208478, 2015). "The importance of this pathway is highlighted by the finding that BRAF and NRAS mutation are the two most important oncogenic mutations in melanoma and both of these mutations result in the constitutive activation of the RAS-RAF-MEK-ERK signaling cascade." (PMID 25646931, 2015). "In melanoma, BCL2A1 is implicated in resistance to BRAF inhibitors further supporting its pro-survival activity." (PMID 26460486, 2015). "Given the prevalence of activating BRAF mutations in cutaneous melanomas, we interrogated eCTC and MTF cultures for somatic activating mutations in BRAF." (PMID 26267609, 2015). "Targeting multiple signaling pathways was more effective in suppressing the growth of BRAF V600E mutant melanoma cells." (PMID 25997619, 2015). "Although apparently unrelated, all these different molecular alterations are able to confer resistance to BRAF or MEK inhibitors in melanoma cells, through their tight interaction with the activity of the RAF–MEK–ERK signaling cascade." (PMID 26322273, 2015). "While we were working with vemurafenib, dabrafenib, another BRAF inhibitor was approved for the treatment of BRAF mutant melanoma." (PMID 26497853, 2015). "The Distance score component of the DCS was calculated over 69,856 induced facts between non-BRAF inhibitor and melanoma concepts." (PMID 26262134, 2015). "Cancers like melanoma have frequent aberrations of the BRAF gene in more than 50% of patients and have three US FDA approved drugs targeting the BRAF V600 E aberration." (PMID 26510912, 2015). "A recent study reported that higher level of autophagy in melanomas patients showed lower response rate to BRAF inhibitor, suggesting closely relationship between autophagy and cancer resistance in clinic." (PMID 26288183, 2015). "A central paradigm of acquired drug resistance in BRAF mutant melanomas is the reactivation of MAPK signaling." (PMID 26029660, 2015).
melanoma (continued). "The BRAF mutant in the circulating DNA of melanoma plasma was successfully detected by ddPCR, which fell with treatment response and rose with detectable disease progression." (PMID 26485760, 2015). "Human BRAF-driven tumors, mostly melanomas, and thyroid and colorectal carcinomas, are biologically and clinically aggressive malignancies, frequently resistant to conventional anticancer therapies." (PMID 26084290, 2015). "Here we report a novel and fully automated IHC assay to screen the BRAF V600E mutation in Chinese patients with CRC, PTC and melanoma." (PMID 25784606, 2015). "Our results suggest that BAY 87-2243 induces an energy crisis in BRAF mutant melanoma cell lines accompanied by the downregulation of the RAF-MEK-ERK signaling cascade, thereby, potentially allowing activation of AMPK and RAPTOR." (PMID 26500770, 2015). "Ventana IHC assay using BRAF V600E (VE1) mouse monoclonal primary antibody was performed to screen for the BRAF V600E mutation in 779 patients, including 611 cases of CRC, 127 cases of PTC and 41 cases of malignant melanoma." (PMID 25784606, 2015). "Next, we examined the expression of molecules associated with cell proliferation in tumors of nude mice subcutaneously injected with BRAF mutated A375 and SK-MEL-28 melanoma cells following treatment with fisetin, sorafenib and the combination." (PMID 26299806, 2015). "In melanoma, distinct RTKs have been involved in BRAF inhibitors (BRAFi) resistance, yet the utility of RTKs expression pattern to identify intrinsically resistant tumors has not been assessed." (PMID 25742786, 2015). "Single treatment of BRAF mutant melanoma cell lines with vemurafenib or dabrafenib (BRAF inhibitors) alone or in combination with trametinib (MEK1/2 inhibitor) resulted in overexpression of Mcl-1." (PMID 26497853, 2015). "Sequential inhibition of the MAPK pathway by combination therapy with dabrafenib (a selective BRAF inhibitor) and trametinib (MEK inhibitor) has been shown to improve the progression-free survival in patients with BRAF V600 melanoma." (PMID 26334521, 2015). "We selected a panel of nine early passage BRAF-mutant melanoma cell lines that were both developed and maintained at low-oxygen tension (5%)." (PMID 26137449, 2015). "In about half of melanomas, presence of BRAF-mutant monomers determines a constitutive activation of the downstream ERK effector." (PMID 26322273, 2015). "We conclude that PLX4032 triggers a sustained induction of RHOB expression in BRAF-mutant melanoma cells." (PMID 26098773, 2015). "The BRAF Inhibitor in Melanoma 1 (BRIM 1) was a two-stage phase I dose-finding study of PLX4032, later known as vemurafenib." (PMID 26328215, 2014). "In melanoma, a potential mechanism by which NFκB signaling is constitutively activated is through the mutant BRAF pathway." (PMID 24466036, 2014). "Toxicities from BRAF inhibitors or anti-CTLA-4 antibodies for melanoma, albeit low grade, are continuous and chronically impact on quality of life." (PMID 25053129, 2014). "Using the Broad-Novartis Cancer Cell Line Encyclopedia we did not see a correlation, however, between BCL2 levels pre-treatment and sensitivity to BRAF inhibition as measured by IC50 across 22 BRAF mutant melanoma cell lines." (PMID 24983357, 2014). "Dabrafenib has since also been approved as the second BRAF inhibitor to achieve FDA approval for the treatment of advanced melanoma." (PMID 25277503, 2014). "Previous studies in commonly used high-passage BRAF-mutant lines have suggested that CRC cells are much less sensitive to vemurafenib than malignant melanoma cells due to an EGFR-mediated reactivation of ERK signaling." (PMID 25309914, 2014). "BRAF mutant melanoma cells were more sensitive to fisetin treatment and this was associated with inhibition of MEK1/2 phosphorylation." (PMID 24466036, 2014).
melanoma (continued). "Very interestingly, one of the identified peptide is a transcription factors trigger cancer epithelial-mesenchymal transition, SLAIN 1 whose expression was modulated by BRAF-mediated ERK activity in melanoma cells." (PMID 25437182, 2014). "The reported analysis of biopsies taken before and after treatment with BRAF or BRAF+MEK inhibitors showed the following: enhancement of melanoma antigen expression, increase in CD8+ TILs, and decrease in immunosuppressive cytokines IL-6 and IL-8." (PMID 24743024, 2014). "BRAFinhibition has been demonstrated to be an effective therapeutic target in melanoma; dabrafenib joinsvemurafenib, an oral BRAF inhibitor, which was FDA approved in 2011." (PMID 25089220, 2014). "The mutational status of BRAF, RAS, GNAQ, GNA11 and KIT genes in Grey horse melanomas was determined by direct sequencing." (PMID 25413220, 2014). "Nevertheless, anecdotal clinical evidence already exist for the successful application of intermittent dosing or re-challenge of BRAF/MEK inhibitors in melanoma patients." (PMID 25344914, 2014). "It has been previously reported that Bim was also critical for apoptosis following KIT inhibition by imatinib in GIST, BRAF V600E inhibition by imatinib in melanoma and EGFR inhibition by gefitinib in non-small cell lung cancers." (PMID 25431951, 2014). "Although there has been remarkable success in using BRAF inhibitors in melanomas with a response rate of over 80%, a lower response rate of about 10% is seen in CRCs." (PMID 25005754, 2014). "In melanoma, Axl is associated with NRAS mutations compared to BRAF mutations, and is inversely correlated with the expression of the microphthalmia-associated transcription factor (MITF)." (PMID 25344858, 2014). "To examine the antiproliferative effects of CH5126766 or PD0325901, we used two melanoma cell lines with mutations resulting in ERK activation, SK-MEL-28 (BRAF V600E), and SK-MEL-2 (NRAS Q61R)." (PMID 25422890, 2014). "Inhibition of XPO1 using KPT-185, -251, -276, and -330 impaired melanoma survival in both BRAF mutant and wild-type melanoma cell lines and in mouse xenografts." (PMID 24503695, 2014). "For BRAFV600 mutant melanoma, initial response rate to BRAF inhibitors (BRAFi) is beyond 50%, though median duration of response is only 6-7 months." (PMID 25142146, 2014). "Specifically, BRAF-mutant melanomas, which show an initial responseto RAF inhibitors, usually become resistant to the therapy." (PMID 25490933, 2014). "BRAF is especially relevant in melanoma progression because of the high frequency of its activating mutations and resistance to its inhibition." (PMID 25503774, 2014). "VEGF axis inhibitors have almost doubled the survival (from 12 to 22 months) of advanced RCC patients, as have BRAF inhibitors for advanced melanoma patients in a second-line setting." (PMID 25245327, 2014). "BANCR was the mutant BRAFV600E-activated long non-coding RNA identified from samples from BRAF-mutant human melanomas." (PMID 24967732, 2014). "For example, BRAF-mutant melanoma cells exposed to vemurafenib develop resistance to the agent by upregulating their BRAF expression." (PMID 25500581, 2014). "In BRAF-mutated melanomas, RAS is negatively regulated by ERK-dependent feedback: BRAF-mutated cells have hyperactive ERK signaling and elevated ERK-dependent transcriptional output, including negative-feedback components." (PMID 25344914, 2014). "We observed that increased pAKT levels at baseline levels were tightly correlated with intrinsic resistance to SCH772984 in the BRAF- mutant melanoma cell lines." (PMID 25142146, 2014). "Next, we searched for CNAs in genes known to be affected by CNAs in melanoma (BRAF, KIT, MITF, CCND1, CDK4, PTEN, CDKN2A and AKT3)." (PMID 24399611, 2014).
melanoma (continued). "The past 3 years have witnessed the addition of four new agents—ipilimumab, vemurafenib, dabrafenib (Tafinlar), and trametinib (Mekinist)—to the therapeutic repertoire for advanced melanoma, two of which are selective BRAF kinase inhibitors." (PMID 26328215, 2014). "MAPK pathway is the main hyper-activated signaling cascade in melanoma, mainly as consequence of mutations in oncogenes such as BRAF and NRAS (the latter being mutated in about 20% of melanomas)." (PMID 24920406, 2014). "Along similar lines, a compound equipotent to dabrafenib but biochemically more selective is predicted to target BRAF(V600E) mutant melanoma more effectively in vivo than current available BRAF inhibiting drugs." (PMID 24651269, 2014). "All these findings support the development of clinical trials evaluating the role of adding agents that target apoptosis, generally, and BH3-mimetics, specifically, in combination with BRAF-directed therapy in patients with BRAF-mutant melanoma." (PMID 24983357, 2014). "Identification of activating BRAF mutations in melanoma tumors has fostered development of the selective small-molecule inhibitor of mutant BRAF kinase vemurafenib for the treatment of advanced melanoma." (PMID 26328215, 2014). "Significant advances in the treatment of melanoma have been made with BRAF-targeted therapy and immune checkpoint blockade, and these strategies are now being combined empirically in clinical trials." (PMID 25941608, 2014). "In mutant BRAF-harboring melanoma cells that are resistant to MAPK inhibitors, MITF is downregulated whereas Axl and NFκB signaling is upregulated." (PMID 25344858, 2014). "An analogy can be made to non-melanoma solid tumors expressing the activating V600E mutant BRAF, where vemurafenib treatment is sometimes ineffective, ie as in the colon." (PMID 24422672, 2014). "Numerous reports have suggested that the inhibition of V600E BRAF signaling blocks melanoma cell proliferation and induces apoptosis in vitro and in vivo." (PMID 25275294, 2014). "Metastatic melanoma treatment has considerably progressed in the past five years with the introduction of targeted therapy (BRAF and MEK inhibitors) and immune checkpoint blockade (anti-CTLA4, anti-PD-1, and anti-PD-L1)." (PMID 25610709, 2014). "BRAF inhibitor–mediated activation of EGFR/SRC family kinase/STAT3 signaling was shown to mediate resistance in BRAF-mutant melanoma cell lines and was confirmed in patient biopsies." (PMID 24743024, 2014). "This is closely related to resistance of melanoma cells to apoptosis, as induction of apoptosis is a major determinant of long-term responses of BRAFV600E melanoma cells to mutant BRAF inhibitors." (PMID 25365078, 2014). "Vemurafenib (PLX4032) is a serine threonine kinase inhibitor specifically targeting mutated BRAF and has recently been approved for treating BRAFV600E mutated melanomas by the US Food and Drug Administration (FDA)." (PMID 24840574, 2014). "Combined BRAF and MEK inhibition, as compared with BRAF inhibition alone, delays the emergence of resistance and reduces toxic effects in patients who have melanoma with BRAF V600E or V600K mutations." (PMID 25374620, 2014). "Occurrence of invasive SCC of the vulva and development of multiple premalignant colonic and gastric adenomas have also been described in patients with BRAF-mutant melanoma treated with vemurafenib." (PMID 26328215, 2014). "Here, we applied an unbiased multi-angle approach to discover new potential targets that render melanoma more sensitive to clinically relevant inhibitors of the BRAF pathway, particularly those targeting BRAF and ERK." (PMID 25538140, 2014). "Recent studies have used small molecule inhibitor arrays to define protein profiles that mediate desensitization of mutant BRAF melanoma cells to BRAF and other kinase inhibitors." (PMID 24980819, 2014).